HRAS (HRas proto-oncogene, GTPase)
Diseases named in the same sentence as HRAS in open-access papers (continued):
Sharing a sentence is not in itself a finding about the gene and the disease.
glioblastoma (18 papers, 2011 to 2025). The most malignant astrocytic tumor (WHO grade IV). "In this context, RAS signaling is of interest because ectopic expression of an activated form of the GTPase HRAS oncoprotein (G12 V) induces massive cytoplasmic vacuolization and caspase-independent cell death in cultured glioblastoma and gastric cancer cells." (PMID 39970625, 2025). "Furthermore, overexpression of constitutively active HRas (HRas G12V) leads to extensive vacuolization in glioblastoma cells, with Ras localized at the limiting membrane of cytoplasmic vacuoles." (PMID 33028008, 2020). "Still, in case of glioblastoma multiforme, HER2 was identified to be a part of cluster 1 also involving other top hub nodes of proto-oncogenes KRAS, HRAS and NRAS." (PMID 31952211, 2020). "Although unproven, it is conceivable that the less frequent clones can provide, altruistically, a fitness advantage to the HRAS mutant cells similarly to what has been observed for glioblastoma multiforme or for WNT-secreting wild-type HRAS clones supporting HRAS mutants." (PMID 33594337, 2021). "Like vacuoles formed during SV40 infection, HRas-induced vacuole formation in glioblastoma cells was independent of ERK signaling and blocked by chemical inhibition of Rac1." (PMID 33028008, 2020). "HRAS is a member of the RAS oncogene family, whose negative effect on Glioblastoma is previously observed on the overall and progression-free survival." (PMID 30059495, 2018).
non-small cell lung carcinoma (18 papers, 2008 to 2025). A group of at least three distinct histological types of lung cancer, including non-small cell squamous cell carcinoma, adenocarcinoma, and large cell carcinoma. "Three different isoforms of RAS proteins have been identified to date (KRAS, NRAS, HRAS) and mutations in KRAS are frequently found in human cancers, among which the Non-Small Cell Lung Cancer (NSCLC)." (PMID 36358848, 2022). "The present study was designed to determine the potential significance and the clinical relevance of two RAS gene family isoforms (KRAS and HRAS) and their mRNA expression levels in the group of non-small-cell lung cancer patients." (PMID 33549031, 2021). "This study emphasized the role of HRAS and KRAS gene expression levels and their heterogeneity in non-small-cell lung cancer cases." (PMID 33549031, 2021).
gastric cancer (17 papers, 2008 to 2025). A primary or metastatic malignant neoplasm involving the stomach. "While low expression level of HRAS was also associated with radiosensitivity in gastric cancer." (PMID 32963532, 2020). "By inducing cellular senescence in gastric cancer cells with bleomycin, we investigated changes in the expression levels of HRAS through western blot." (PMID 37341987, 2023). "Ectopic expression of HRAS was shown to promote the proliferation, migration, invasion, angiogenesis and clone formation of gastric cancer cells." (PMID 33987081, 2021). "In conclusion, this study suggests that RAF1 rs3729931, HRAS rs45604736, MAPK1 rs2283792, and MAPK1 rs9610417 are associated with gastric cancer." (PMID 30597917, 2018). "We found significant association of the SNPs RAF1 rs3729931, HRAS rs45604736, and MAPK1 rs2283792 and rs9610417 with gastric cancer." (PMID 30597917, 2018). "In conclusion, using a case-control approach we found that rs3729931 (RAF1), rs45604736 (HRAS), rs2283792, and rs9610417 (MAPK1) are associated with gastric cancer." (PMID 30597917, 2018). "Increased HRAS expression levels promote gastric carcinoma cell aggressiveness." (PMID 35422066, 2022). "Immunoblot analysis of RAS proteins revealed that the expression of KRAS was increased in KRAS-amplified gastric cancer cells (HSC45, SH101P4 and MKN1), while neither NRAS nor HRAS were highly expressed (data not shown)." (PMID 19545448, 2009).
lung adenocarcinoma (17 papers, 2009 to 2024). A carcinoma that arises from the lung and is characterized by the presence of malignant glandular epithelial cells. "OncoMap also identified an HRAS mutation in a lung adenocarcinoma and an NRAS mutation in a colorectal adenocarcinoma." (PMID 19924296, 2009). "In addition, HRAS mutations seem to be more frequent in squamous cell cancer of the lung (2.8%) than in adenocarcinoma of the lung (1%)." (PMID 26544513, 2015). "One recent report described an adenocarcinoma of the lung with HRAS Q61L mutation suffering from rapid progression and deterioration suggesting that HRAS mutations in NSCLC tumors might be aggressive and associated with poor overall prognosis, similar to KRAS mutant NSCL." (PMID 26544513, 2015). "The most common type of mutation in EGFR is exon 19 E746_S752delinsV, an extremely rare mutation in EGFR mutant lung adenocarcinoma; KRAS and HRAS mutations are at codons 12 and 13; all AKT 1 mutations are restricted to the E17K mutation." (PMID 38115282, 2023). "For the Ras proteins, KRAS/HRAS/NRAS all harbor highly recurrent mutations for residues p.G12/G13 that affect large fractions of pancreatic adenocarcinoma (PAAD), COAD, READ, lung adenocarcinoma (LUAD), and UCEC." (PMID 33875650, 2021). "Codons 12, 13, or 61 are typically mutated in KRAS; similar mutations affect homologous genes HRAS and NRAS, though infrequently for lung adenocarcinomas." (PMID 29322935, 2017). "Briefly, among newly detected mutations in lung adenocarcinoma, AKT, BRAF, FGFR2, HRAS, and KIT mutations were detected in one sample (1.3%), MAP2K in two samples (2.6%), MET in 4 samples (5.9%), and FGFR3 in 5 samples (7.4%)." (PMID 28404952, 2017). "Mutations in the RAS protein subfamily (HRAS, NRAS, KRAS) occur frequently in various types of cancer and have a relatively high frequency in lung adenocarcinomas." (PMID 26170901, 2015). "In addition, our in silico analysis found a significant inverse correlation between HRAS and KRAS dependency in KRAS-G12C mutant lung adenocarcinoma suggesting that these two proteins can play a compensatory role in tumor growth." (PMID 38278976, 2024).
neuroblastoma (17 papers, 2006 to 2024). Neuroblastoma (NB) is the most common solid, extracranial childhood tumor. "In line with our in vitro data, we detected de novo NF1 and NRAS or HRAS mutations in neuroblastomas from patients treated with the ALK inhibitors, ceritinib or lorlatinib, at resistance development." (PMID 35689207, 2022). "Eleven of the shortlisted genes were downregulated in cisplatin-resistant tumours, low expression was found to be unfavourable in neuroblastoma, one gene, HRAS, was upregulated in cisplatin-resistant tumours, and high expression was found to be unfavourable in neuroblastoma." (PMID 38809883, 2024). "Mapping the upstream regulator networks that drive DE genes in highly MNA cells compared with MYCN single copy cells elucidated several central nodes not previously linked to MNA neuroblastoma (e.g. HRAS, MAPK1, RAF1, NEUROG1 and ER)." (PMID 26673823, 2015). "The Ras family proteins HRAS and NRAS, comprised in the term “prenylation”, were significantly upregulated in ALT-positive neuroblastomas." (PMID 33627664, 2021). "Non-silent SNVs (2–6 per tumour) in cancer-related genes (HRAS, ALK and ATM) occurred exclusively in high-risk neuroblastomas and were clonal in a subset of patients but also spatially or temporally heterogeneous in others." (PMID 34815394, 2021). "Moreover, neither HRAS nor HRAS has any mutations, suggesting that Erastin or RSL3 treatment leads to ferroptosis processes independent of RAS mutations in neuroblastoma N2A cells." (PMID 34445601, 2021).
ovarian carcinoma (17 papers, 2015 to 2025). A malignant neoplasm originating from the surface ovarian epithelium. "In our research, we noted an over 1000-fold increase in the expression of the HRAS gene in fibroblasts after the treatment with exosomes derived from untreated ovarian cancer cells." (PMID 36012171, 2022). "The available studies show that the expression of the HRAS gene (V-Ha-ras Harvey rat sarcoma viral oncogene homolog) is strong in ovarian cancer cells." (PMID 36012171, 2022). "Significant changes in gene expression in fibroblasts after treatment with exosomes from ovarian cancer cells were observed for HRAS and SET (SET nuclear oncogene)." (PMID 36012171, 2022). "Inhibition of the increase in HRAS expression in cells targeted for the development of metastatic processes may significantly limit the development of metastatic foci of ovarian cancer." (PMID 36012171, 2022). "The observed differences in expression of the HRAS gene (V-Ha-ras Harvey rat sarcoma viral oncogene homolog) were significant depending on whether the fibroblasts were treated with exosomes derived from untreated or drug-treated ovarian cancer cells." (PMID 36012171, 2022). "let-7 suppresses multiple ovarian cancer oncogenes including KRAS, HRAS, c-MYC, and HMGA-2." (PMID 32256980, 2020). "Let-7 suppresses several oncogenes, such as KRAS, HRAS, and c-MYC, in ovarian cancer." (PMID 26779370, 2015).
glioma (16 papers, 2008 to 2023). A benign or malignant brain and spinal cord tumor that arises from glial cells (astrocytes, oligodendrocytes, ependymal cells). "Recent results have further demonstrated that SHP-2 binds and dephosphorylates both wild-type and oncogenic HRAS on Tyr32 in astrocytes and glioma cells, an event that increases RAS association with RAF-1 and downstream MEK/ERK activation." (PMID 27582544, 2016). "Indeed, several mouse models of glioma have causally implicated activated HRas and KRas in glioma formation." (PMID 18985151, 2008). "Mutations in KRAS, HRAS and NRAS are known in gliomas and are often concomitant with BRAF mutations and fusions." (PMID 37490467, 2023). "Additionally, the expression levels of HRAS, MAPK1, IGF1, and IGF1R in glioma cells have been closely linked to the growth, invasion, and metastasis of glioma." (PMID 37865727, 2023). "These pathways have inspired numerous glioma models based on the retroviral expression of PDGF-B, HRAS-G12V, AKT, and IDH1-R132H." (PMID 34884748, 2021).
oral cancer (15 papers, 1991 to 2025). "Our data reveal a significantly higher prevalence of HRAS mutations in South Asia, corroborating previous studies on oral cancer in India." (PMID 35600380, 2022). "In addition to oral cancers, many other mutated genes, including HRAS and MLH1, exist in other cancer types." (PMID 39729421, 2024). "The HRAS mutation frequency is higher in oral cancer worldwide." (PMID 35600380, 2022). "In the oral cancer cells (HSC4, OSC19) that were used in this study, high expression of EGFR was confirmed, but no mutations of BRAF, HRAS, KRAS, and NRAS were observed." (PMID 32878053, 2020).
prostate carcinoma (15 papers, 2013 to 2026). A carcinoma that arises from epithelial cells of the prostate gland. "The panel generated from this approach identified as top candidates mutations in known driver genes (e.g. HRAS) and prostate cancer related transcription factor binding sites (e.g. MYC, AR)." (PMID 32859160, 2020). "Together, our data indicate that modulation of HRAS splicing can impact cell proliferation in prostate cancer cells." (PMID 37399401, 2023). "Here, we report that large-scale bioinformatic analyses of splicing and MYC expression confirm the correlation of HRAS exon 5 repression with the MYC signature score in prostate cancer and across many tumor types." (PMID 37399401, 2023). "To examine whether other exons that are regulated by hnRNPs H and F are also regulated by MYC, similarly to HRAS, we analyzed RNA-seq data from a prostate cancer model carrying a doxycycline-inducible MYC gene." (PMID 37399401, 2023). "The differential splicing of gene HRAS may suggest the roles of expression change at isoform level in prostate cancer." (PMID 30367578, 2018). "We found that HRAS exon 5 is one of a group of MYC-regulated exons that are also regulated by hnRNPs H and F, which are essential for the growth of prostate cancer cells." (PMID 37399401, 2023).
skin tumors (14 papers, 2012 to 2025). "KRAS stands out as the predominant mutation in non-small cell lung cancer (NSCLC), while HRAS mutations are prevalent in skin cancer." (PMID 38247798, 2024). "In the 4th edition of the 2018 WHO classification of skin tumors, lesions in the spitzoid pathway (pathway 4) are characterized by mutations in HRAS, tyrosine kinase fusions (ALK, ROS1, RET, NTRK1/3, and MET), or serine-threonine kinase fusions (BRAF, MAP3K8)." (PMID 33040161, 2021). "Other proteins (AKT, ERBB2, HRAS, and CCND1) are also reported to have a part in skin cancer." (PMID 34466445, 2018).
cervical carcinoma (13 papers, 2012 to 2025). A carcinoma arising from either the exocervical squamous epithelium or the endocervical glandular epithelium. "The protein–protein interaction study indicates the interacting partners of EREG, and they were EGF, TGFA, GRB2, and HRAS, and most of them regulate cervical cancer." (PMID 34439555, 2021). "Interestingly, zardaverine and analogs showed a similar cytotoxicity profile in CS242 ERMS and cervical carcinoma-derived HeLa cells, suggesting a mechanism of action common to both cell types that does not require the presence of an HRAS mutation (HeLa contains wild type HRAS)." (PMID 28421158, 2017). "The expression of seven hub genes in the PI3K/AKT/mTOR pathway were increased in cervical cancer: EIF4EBP1, GSK3B, HRAS, KRAS, NRAS, PIK3CB and PIK3R2." (PMID 36911370, 2023). "Various genes, namely GLS, CD36, WNT5a, HRAS, DDB2, PIK3R2, and CDH2 were found to be differentially highly expressed in primary cervical cancer samples of patients who developed distant recurrence." (PMID 35087740, 2021). "Namely, GLS, CD36, WNT5a, HRAS, DDB2, PIK3R2, and CDH2 were significantly DE between cervical cancer without recurrence and cervical cancer with distant recurrence." (PMID 35087740, 2021).
liver cancer (13 papers, 2011 to 2024). An epithelial or non-epithelial malignant neoplasm that arises from the liver. "Among three Ras genes KRAS, NRAS, and HRAS, NRAS and HRAS mutations are more common in liver cancer." (PMID 33854636, 2021). "In liver cancer, activating mutations in KRAS and NRAS are found considerably more frequently than in HRAS." (PMID 26799184, 2016). "For example, the HRAS oncogene showed a 5-fold expression difference between the four regions of liver cancer." (PMID 27010638, 2016). "Furthermore, HRAS overexpression plays a significant role in the development of liver cancer." (PMID 33854636, 2021). "In summary, these data indicated that both PLK1 and HRAS expression levels increase during HCC development and remain elevated in (advanced) liver cancer in vitro and in vivo." (PMID 29423069, 2018). "As for the limitations of the current study, although the EGFR downstream effector RAS is a major proto-oncogene for human cancer, the RAS mutation is not very prevalent in patients with liver cancers, with 7% of patients having KRAS mutations and 4% of patients having HRAS mutations." (PMID 38791872, 2024).
pheochromocytoma (13 papers, 1998 to 2024). "Gene expression microarray profiling showed that these tumors clustered with NF1-, RET,- and HRAS-mutated pheochromocytomas, indicating activation of the MAPK and PI3K-AKT signal transduction pathways." (PMID 29159601, 2018). "In pheochromocytoma and paraganglioma (PCPG), 0.64% of mutations were recurrent HRAS p.Q61R, and 0.36% were CHEK2 p.K152E." (PMID 30890735, 2019). "Besides RET and HRAS, FGFR1 is only the third protooncogene found to be recurrently mutated in pheochromocytomas." (PMID 29159601, 2018). "Our findings are consistent with the hypothesis that mutations in HRAS and inherited PCC/PGL genes are mutually exclusive driver mutations (though comprehensive analysis of all inherited phaeochromocytoma/PGL genes has not been undertaken in all patients)." (PMID 25883647, 2015).